CD2 (CD2 molecule)
Diseases named in the same sentence as CD2 in open-access papers (continued):
Sharing a sentence is not in itself a finding about the gene and the disease.
tumor (continued). "An eighth group, composed of cases with underlying features of the MF, MS, CD1, CD2, HY and LB subtypes, but also a strong overwhelming myeloid signature, most likely driven by the co-purification of myeloid cells from bone marrow samples with low tumor cell infiltration belong to MY group." (PMID 33572851, 2021). "Tumor cells expressed T-cell markers (CD2, CD3, CD5, CD7; heterogeneous) and cytotoxic markers (TIA-1) and showed CD30 and CD56 positivity, with EBV positivity confirmed by EBER in situ hybridization." (PMID 41744967, 2026). "Coimmunoprecipitation analysis of tumor tissues revealed weakened CD2–CD58 interactions in the sh‐CD2 CTL group, as indicated by reduced CD58 band intensity." (PMID 40859981, 2025). "Western blotting further validated a marked decrease in ASS1 protein levels and a concomitant upregulation of CAD expression in tumor tissues derived from the sh‐CD2 group." (PMID 40859981, 2025). "Phenotypically, the tumor cells in the lymph nodes were positive for CD2, CD3, and CD20 with CD4/8 double negativity." (PMID 40270601, 2025). "In the subcutaneous tumor model, mice in the sh‐CD2 CTL group exhibited significantly increased tumor volume and weight compared to the sh‐NC CTL group." (PMID 40859981, 2025). "By inducing exhaustion in CAR-T cells through multiple rounds of stimulation with tumor cells, we observed a progressive decrease in CD2 expression on T cells as exhaustion progressed." (PMID 40615696, 2025). "Key immune activation and tumor suppression genes including CD2, CD3, CD247 (CD3 zeta chain), CD48, CD84, CCL19, CXCL10, and SLAMF6 were consistently upregulated in the hot phenotype across all ancestries." (PMID 41387728, 2025). "Functional experiments further confirmed that CD2 deficiency significantly impaired CTL proliferation, activation, and cytotoxic capacity while enhancing tumor cell proliferation, migration, and immune evasion." (PMID 40859981, 2025). "Compared to pretreatment samples, T cells from TCE-treated patients exhibited reduced cytokine production following stimulation with anti-CD2/3/28 antibodies or viral peptides and reduced activation/tumor lysis in tumor-T cocultures." (PMID 40762835, 2025). "In contrast, CTLs with intact CD2 expression exhibited stronger antitumor activity, reinforcing the critical role of CD2 in maintaining CTL‐mediated tumor control." (PMID 40859981, 2025). "Research indicates that the IS established by the cooperation between CD58 of tumor cells and CD2 with CAR-T cells is essential for enhancing the cytotoxic efficacy of CAR-T cells." (PMID 40365344, 2025). "To further investigate the effect of CD2‐deficient CTLs on BCBM, we established both subcutaneous and brain metastasis models in mice to evaluate their impact on primary tumor growth and metastatic progression." (PMID 40859981, 2025). "By establishing a CD2‐knockdown CTL‐MDA‐MB‐231 coculture system and validating results in both subcutaneous and brain metastasis mouse models, we comprehensively evaluated the role of CD2 in tumor immune surveillance." (PMID 40859981, 2025). "EGFR-BBζ CAR-T-cell therapy resulted in minimal tumor growth control, while tumor growth in the EGFR-BBζ + CD2 treatment group was markedly suppressed." (PMID 40615696, 2025). "Compared with CAR-T-19 cells, CD19-BBζ + CD2 CAR-T cells presented enhanced tumor suppression efficacy and sustained cellular persistence." (PMID 40615696, 2025). "To evaluate the effect of ectopic CD2 expression on CAR-T-cell–tumor cell interactions, we measured avidity via dynamic ultrasound microscopy (z-Movi)." (PMID 40615696, 2025). "First, by coculturing Jurkat cells stably expressing CAR19 (J-CD19-BBζ) with Nalm6 tumor cells, we observed significant CD2 clustering in the region where CAR molecules aggregated, providing direct evidence of the involvement of CD2 in IS formation." (PMID 40615696, 2025).
tumor (continued). "To investigate the impact of CD2 downregulation on tumor cell metabolism, we analyzed changes in pyrimidine metabolism and urea cycle‐related molecules in MDA‐MB‐231 cells and tumor tissues from BCBM mice using LC‐MS and western blot." (PMID 40859981, 2025). "In the in vivo experiments, tumor tissues from sh‐CD2 group mice showed significantly higher TTP, CTP, and TTP + CTP levels, along with a pronounced reduction in Arg levels compared to the sh‐NC group." (PMID 40859981, 2025). "TUNEL staining revealed that the proportion of apoptotic cells in tumor tissues was significantly reduced in the sh‐CD2 CTL group relative to controls." (PMID 40859981, 2025). "In this review, we focus on the roles of CD226 and CD2 in modulating the responses of T cells, especially within the context of tumor immunity." (PMID 39349829, 2024). "Recent advances in antibody engineering technology have led to the development and evaluation of T-cell engager antibodies with tri-specificity for CD3, CD2, and tumor antigens at the preclinical level." (PMID 39349829, 2024). "This review explores the roles of CD226 and CD2 in regulating T cell responses, particularly in tumor immunity." (PMID 39349829, 2024). "Analysis of the interaction dynamics between CD19 CAR T cells and Nalm6 tumor cells utilizing time-lapse imaging microscopy in nanowell grids (TIMING) revealed that CD2 contributes to the directional migration of CAR T cells." (PMID 39349829, 2024). "In particular, the Tumor Presence Signature (TPS) herein described shows an AUC of 0.788 resulting from cumulative ROC curve analysis involving CD2, CD3, CD56 and CD146, thus delineating their common involvement in LCa cancer onset and progression." (PMID 38902710, 2024). "5FU/IL2/CD2 nanoplexes achieved better histopathological values considering primary tumor foci and the mean number of metastatic foci." (PMID 36839637, 2023). "UCART2 demonstrated potent cytotoxicity against all three CD2+ tumor cell lines in vitro (p < 0.0001)." (PMID 37798328, 2023). "CD2 expression in lymphocytes can induce apoptosis, promote immune activation, inhibit tumor cell proliferation, and support tumor regression." (PMID 38125769, 2023). "While NK cell adhesion to tumor cells is mediated by integrin αLβ2, NK cells use integrin αMβ2 and receptor CD2 to interact with ICAM-4 and CD58 on iRBC, respectively." (PMID 37939134, 2023). "The number of CD8 + TILs per gram in both tumour models from CD2-Egr2/3-/- mice were much less than GFP-Egr2 knockin mice." (PMID 36342511, 2023). "While platelets clearly inhibited cytolytic release of activated CD8+ T cells, except for Granzyme B, tumour cell-induced platelet releasates further enhanced the activation with CD3/CD28/CD2 stimulating antibodies." (PMID 35285006, 2022). "The overall survival and chemotherapy response of LSCC patients have been predicted by models consisting of histopathological factors (CA199, CA724), genes (CD48, CD2), radiomics, and clinical factors (tumor differentiation, age, and stage)." (PMID 36135078, 2022). "Lymphocytes in the intra-epithelial compartment are described as having a phenotype that is similar to or consistently discordant with that of the invasive tumor and they must also express some pan-T-cell markers such as CD2, CD3, CD5, CD7." (PMID 36451465, 2022). "Tumor cells typically exhibit a CD2+/−, cytoplasmic CD3+, CD4−, CD7+, CD8−, CD56+, CD103−, and TIA1+ phenotype." (PMID 34830926, 2021). "The data demonstrates that the best performing immunotranscriptomic model is the one based on the CD14/CD2 ratio, emphasizing both the tumor phagocytosis mechanism and the anti-tumor immune response, yielded an AUC of 0.70." (PMID 34685549, 2021). "Tumor-derived Jurkat T cells preactivated with anti-CD2/CD3/CD28 antibodies strongly responded to the micro-arc CaP coating and showed a 4.5-fold upregulation of hTERT gene expression after 14-day culture." (PMID 34279263, 2021).
tumor (continued). "It is possible that CaP-coated Ti samples only enhanced preliminary stimulation of 14-day proliferative tumor cells with anti-CD2/CD3/CD28 antibodies." (PMID 34279263, 2021). "CAR binding to its target-Ag will induce CD2 signaling independently of CD58 expression by the tumor cells." (PMID 34809678, 2021). "Preactivation of Jurkat T cells with anti-CD2/CD3/CD28 antibodies that mimic the stimulating signal produced by APCs led to a statistically increased viability of tumor-derived cells after 14 days of culture." (PMID 34279263, 2021). "Tumor-derived Jurkat T cells preactivated with anti-CD2/CD3/CD28 antibodies and contacted with the micro-arc CaP coating for 14 days showed a 4.5-fold upregulation in hTERT expression compared with activated malignant cells cultured without test samples." (PMID 34279263, 2021). "To extend our understanding of the T cell-specific effects of LSP1 during tumor development, we generated transgenic (Tg) mice that specifically overexpress Lsp1 in T cells using CD2 promoter, as described in ‘Materials and methods’ section." (PMID 33020243, 2020). "T cells (expressing Cd2, Cd3e, Cd3g, and Cd6) were the most abundant immune cell type in tumor tissues, followed by cytotoxic cells (expressing Gzma and Klrd1)." (PMID 32612611, 2020). "The fact that CMs have higher expression of PD-L1 and CD2 is most likely due to an anticancer immune response, as is usually indicated by tumor-infiltrating lymphocytes." (PMID 33003444, 2020). "In this cohort, moderate relationships between the resistance of tumor cells to doxorubicin and expression of T-cell markers (CD2, r = 0.42 and CD16, r = 0.50) were found." (PMID 31067780, 2019). "In only one tumour high expression levels of CD2, CD3, CD4, CD8 CTLA-4 and PD-1 were found, suggesting an inflammatory phenotype (not shown)." (PMID 31747973, 2019). "The first goal of this study was to determine if the tumor transplants generated from As3+ and Cd2+-transformed UROtsa cells display a gene expression pattern similar to the basal or luminal subtypes identified by Choi and coworkers for MIBC." (PMID 30550540, 2018). "The tumor cells morphologically resemble large granular lymphocytes and are sometimes pleomorphic and large and immunophenotypically CD2+ surface CD3-, CD3epsilon+, CD16+, and CD56+, with a lack of myeloid and B-cell markers." (PMID 30364049, 2018). "MM tumor cells were purified using the Rosette Step MM purification kit, which removes other contaminating hematopoietic cells that contain CD2, CD14, CD33, CD41, CD45RA, CD66b markers and glycophorin A on red blood cells (RBCs)." (PMID 30383785, 2018). "miRs targeting the neural tumor suppressors pros or brat were used for tumor induction and those targeting CD2 were used as control." (PMID 30479273, 2018). "The variation in expression of the 25 MIBC marker genes plus p63 and KRT17 was determined for the tumor transplants generated from the six independent isolates of the As3+ and seven independent isolates of the Cd2+ -transformed UROtsa cells." (PMID 30550540, 2018). "Expression and localization of luminal protein markers in different histological areas of the As3+ and Cd2+ tumor transplants." (PMID 30550540, 2018). "An example of staining for each basal marker is shown for one tumor generated from the As3+ (As#3) and Cd2+ (Cd#3)-transformed UROtsa cell line." (PMID 30550540, 2018). "The tumor transplants generated by the As3+ and Cd2+-transformed UROtsa cells all clustered with the basal subtype of MIBC." (PMID 30550540, 2018). "The tumor samples from the As3+ and Cd2+-transformed cell lines were shown to be at the same levels of the MIBCs in the PC2 axis." (PMID 30550540, 2018). "While only a subjective observation by the authors’, the variation of expression for each gene within and between the As3+ and Cd2+ generated tumors was surprising low considering each tumor would be expected to have a variable content of stromal components." (PMID 30550540, 2018).
tumor (continued). "Localization of basal protein markers in different histological areas of the As3+ and Cd2+ tumor transplants." (PMID 30550540, 2018). "The tumor cells in PCALCL possess an activated T-cell phenotype and express CD2, CD4, and CD45RO, with a loss of CD2 and CD5 occurring variably." (PMID 29915722, 2018). "The staining of KRT7 was similar in both the well-differentiated and less differentiated areas of tumor for the tumors generated from Cd2+- transformed UROtsa cells." (PMID 30550540, 2018). "The immuno-histochemical staining of the basal markers in the tumor samples reinforced the basal identity of the tumors derived from the As3+ and Cd2+-transformed UROtsa cells." (PMID 30550540, 2018). "Altogether, these data suggest that LFA-3/CD2 interactions promote the survival of CLL cells in the tumor microenvironment." (PMID 28881725, 2017). "Of the many genes encoding molecules that are potentially involved in the adhesion between tumor-associated macrophages and CLL cells, transcriptomic and phenotypic analyses indicated that the receptor/ligand pair LFA-3/CD2 was most relevant in this context." (PMID 28881725, 2017). "Depletion of CD8+ T cells in CD2–Tff2 mice treated with AOM/DSS resulted in a marked (10-fold) increase of tumour growth, indicating that the protective effect of Tff2 overexpression depended on CD8+ T-cell immunity." (PMID 26841680, 2016). "Five months after AOM/DSS treatment the proportion of splenic MDSCs was lowest in the CD2–Tff2 mice that also developed significantly fewer tumours." (PMID 26841680, 2016). "It was revealed that the following immune related factors were key factors being commonly up-regulated for old tumor bearing hosts compared to all younger age groups: CD2, CD3ε (or CD3E), CCL19, and CCL5." (PMID 26497558, 2015). "CD7 and CD2 are expressed in varying degrees, and in approximately half of all cases, tumor cells are CD68+ and exhibit a specific cytoplasmic granular shape (i.e., multifocal color imaging of the Golgi apparatus)." (PMID 25663917, 2015). "All key molecules in the spleen of tumor bearing old hosts (CD2, CD3ε, CCL19, and CCL5) (also been reported to exist in the spleen) leads to immune cell survival and function through increased T-cell survival and activity." (PMID 26497558, 2015). "The tumor cells were positive for CD3ε in 11 cases (11/13, 84.6 %) and positive for CD2 in 6 cases (6/13, 46.2 %)." (PMID 24952511, 2014). "As expected, the Runx genes (Runx2 and Runx3) and Myc family targets (Myc, Mycn) conformed to this pattern, being selected in CD2-MYC and CD2-Runx2 respectively and effectively disappearing from the double transgenic tumours." (PMID 24586197, 2014). "High copy RIS mapping to Runx2 or Runx3 were almost ubiquitous in, but exclusive to, CD2-MYC tumours (P = 0.0001, Fisher's Exact Test)." (PMID 24586197, 2014). "In this regard, it is noted that the bias towards Myc family insertions was less marked here than in a Southern blot-based analysis of a larger CD2-Runx2 tumour cohort." (PMID 24586197, 2014). "This apparent difference in the mode of tumour acceleration is interesting as CD2-Runx2 mice harbour an expanded population of transformation-prone thymocytes, which has no parallel in CD2-MYC mice, most of which remain healthy with no obvious abnormality." (PMID 24586197, 2014). "Immunophenotypically, the malignant tumour cells, like the natural killer cells from which they originate express CD2, cytoplasmic CD3 and CD56." (PMID 23327615, 2013). "We observed an increase in the levels of CD2 only in cancer tissue, when the immune response is almost unable to fight the tumor." (PMID 24348178, 2013). "The tumor cells are positive for one or more pan-T-cell antigens (CD2, CD3, CD5, or CD7) and CD20 with monoclonal rearrangements of TCR γ or β without rearrangement of the IgH gene." (PMID 23031227, 2012).
tumor (continued). "Lentiviral transduction of the chimeric gene combined to flow cytometry sorting of CD2-positive live cells allow rapid production and selection of luciferase-positive cells derived from both lymphoid and epithelial tumor cells." (PMID 21435248, 2011). "PTCL is diagnosed when tumor cells express the mature T cell antigens CD2, CD3, CD4, CD5, CD6, or CD7 on immunohistochemical staining." (PMID 21310044, 2011). "Long-term, stable expression of this chimera is readily obtained in various human tumor cell lines by lentiviral transduction combined to flow cytometry sorting using an antibody directed to the rat CD2." (PMID 21435248, 2011). "Cd2+- and As3+-transformed cells grown in serum-containing growth medium, as well as the derived tumor heterotransplants, overexpressed keratin 6a mRNA and protein compared with UROtsa cells grown in serum-containing growth medium." (PMID 18414623, 2008). "The previous finding that tumor heterotransplants generated from Cd2+- and As3+-transformed UROtsa cells had increased squamous differentiation also correlates with the enhanced expression of keratin 6a." (PMID 18414623, 2008). "It was also shown that the tumor heterotransplants produced by the Cd2+- and As3+-transformed cells had histologic features consistent with human transitional cell carcinoma of the bladder." (PMID 18414623, 2008). "The second goal was to determine the expression of the keratin 6a gene in tumor heterotransplants derived from the As3+- and Cd2+-transformed UROtsa cells." (PMID 18414623, 2008). "We also prepared total RNA and protein lysates from subcutaneous tumor heterotransplants generated from the Cd2+- and As3+-transformed isolates that were originally generated from UROtsa cells grown in both serum-containing and serum-free growth medium." (PMID 18414623, 2008). "To further confirm whether CD2-CAR-T cells prevent or delay tumor cell escape triggered by low antigen expression, we established a mouse model by mixing Raji-luc-WT and Raji-luc-CD19-low cells at a 1:1 ratio." (PMID 40615696, 2025). "Notably, the cytotoxicity of conventional CAR-T cells to tumor cells significantly decreased as the antigen density decreased, whereas CD2-CAR-T cells effectively maintained decent sensitivity to low-density antigens." (PMID 40615696, 2025). "Notably, CD2 expression on CAR-T cells gradually decreased after repeated stimulation by tumor cells, whereas CD19-BBζ + CD2 CAR-T cells maintained significantly increased levels of CD2 expression." (PMID 40615696, 2025). "To determine whether the optimization of IS through CD2 overexpression could subsequently translate into enhanced antitumor efficacy, we assessed the tumor lysis ability of CAR-T cells across various systems." (PMID 40615696, 2025). "Collectively, these findings suggest that supplementing CAR-T cells with exogenous CD2 could further optimize the morphology of the IS, increase its affinity for tumor cells, and diminish the frequency of contacts, notably those that are noncytotoxic." (PMID 40615696, 2025). "In parallel, LC–MS and western blot analyses were conducted to assess the expression of key enzymes involved in pyrimidine biosynthesis and the urea cycle in MDA‐MB‐231 cells and tumor tissues, thereby elucidating the role of CD2 in tumor metabolic reprogramming." (PMID 40859981, 2025). "The γ/δ+ lymphocytic tumor cells displayed a complete loss of CD2, partial downregulation of CD5, and showed no expression of CD4, CD30, CD56, TdT, or TCRαβ (clone 8A3/BetaF1)." (PMID 39091627, 2024). "Despite the suggested role of the CD2‒CD58 axis in preventing T-cell dysfunction, how CD2 costimulation regulates tumor immunity remains unknown." (PMID 39349829, 2024). "In addition to the role of CD2 as an adhesion molecule, the costimulatory activity of CD2 is also required to enhance T-cell responses against tumor cells." (PMID 39349829, 2024). "Expression of CD58 and ligation to CD2 is required for anti‐tumour immunity." (PMID 39054569, 2024).